FOS (Fos proto-oncogene, AP-1 transcription factor subunit)
Diseases named in the same sentence as FOS in open-access papers (continued):
Sharing a sentence is not in itself a finding about the gene and the disease.
cancer (continued). "FOS protein expression can also be activated in patients with cancer, and while we carefully excluded patients with a history of cancer, it is possible that some participants had had undiscovered cancer." (PMID 34858201, 2021). "The network revealed that CRC-related DERs such as hsa-miR-1-3p, hsa-miR-490-3p, hsa-miR-542-5p, hsa-miR-424-5p, and hsa-miR-133a-3p are associated with the regulation of several cancer-related pathways by targeting TIMP3, FOS, PPP1R12B, CCND2, and EGFR." (PMID 32153636, 2020). "Among them, six transcription factors regulating the cancer stem cell-associated genes were verified by the reported literatures (marked with deep red), including NR4A1, FOS, KLF-4, GLI1, NFATC1 and JUN." (PMID 32242101, 2020). "MAPK signalling pathway (JUN, RAC1, MAPK8, MYC and FOS) and transcriptional misregulation in cancer (CDKN1A, MYC and FOXO1)." (PMID 32457348, 2020). "Previous studies have revealed that c-FOS can mediate multiple aspects of cancers, including proliferation, invasion, metastasis, angiogenesis and apoptosis." (PMID 33117720, 2020). "While little is known about the functional involvement of BRWD3 and PECR in human cancers, an enrichment of FOS as part of a heterodimer with JUN has previously been linked to anchorage-independent cell growth in our HPV-transformed cell lines as well as HeLa." (PMID 32188026, 2020). "On the one hand, different from those in the HD-MSCs group, AA-MSCs highly expressed proinflammatory and cancer-associated genes (IL1B, IL-24, CXCLs, FOS, KLK10)." (PMID 32054519, 2020). "Studies with cancer patients have shown that FOS upregulation was correlated with the increase in cell death." (PMID 32379844, 2020). "Among these genes, EGR1, Fos Proto-Oncogene (FOS), FosB Proto-Oncogene (FOSB), Jun Proto-Oncogene (JUN), Dual Specificity Phosphatase 6 (DUSP6) and CTGF have been previously implicated in cancer metastasis." (PMID 30792382, 2019). "Drugs of arsenic trioxide, vinblastine and LGD-1550, interacting with JUN, along with nadroparin that interacts with FOS, all have anti-cancer activities." (PMID 29321498, 2018). "In sum, we concluded that endogenous OCT4A in somatic cancer cells directly bound to the enhancer/promoter regions of the FOS gene." (PMID 29789579, 2018). "Taken together, we demonstrated here that OCT4A is a TF for FOS and positively regulates its transcription via binding to the enhancer region of the FOS gene in somatic cancer cells." (PMID 29789579, 2018). "Taken together, we resolve the long-standing controversy and uncertainty in the field, and reveal a fundamental role of OCT4A protein in regulating FOS/AP-1 signaling-centered genes that mediate the adhesion, migration, and propagation of somatic cancer cells." (PMID 29789579, 2018). "The FOS gene has been found to overexpressed in several cancer types and considered as a proto-oncogene." (PMID 30559931, 2018). "The majority of EGF inducible protein coding genes show a general reduction in expression in these cancer samples (as exemplified by FOS), and the same was observed for EGF-inducible lncRNAs." (PMID 28732076, 2017). "Both mRNA and immunohistochemical data suggest a crucial role in angiogenic cancers for FBJ murine osteosarcoma viral oncogene homolog (FOS), a protein involved in cell proliferation, remodeling, and inflammation." (PMID 26873439, 2016). "Genes associated with cancer development were also significantly increased including JUN, FOS and M2 macrophage markers." (PMID 26448646, 2015). "In contrast, among 10 tumors (#1-10) from the same set of samples, the mRNA expression of its targets (EZH2, MCL-1 and FOS) was significantly higher in cancer tissues." (PMID 25153722, 2014).
cancer (continued). "On the other hand, FOS was thought to enhance proliferation, motility and invasiveness of cancer cells, and have oncogenic role in promoting the development of EMT." (PMID 25153722, 2014). "Later studies might have assessed the combination of FOS-targeted therapies with existing treatments to improve macrophage-based cancer immunotherapy outcomes." (PMID 40936936, 2025). "Among the DEGs positively modulated in SCE17-exposed cells, we can highlight genes involved in cancer progression, such as FOS, JUN, and JUNB proto-oncogenes, Cyclin Dependent Kinase Inhibitor 1A (CDKN1A), and Tumor Protein 53 Inducible Nuclear Protein 1 (TP53INP1)." (PMID 41440891, 2025). "As a major member of the proto-oncogene activator protein-1 (AP-1) family, c-Fos, encoded by the FOS gene, is known to regulate key cellular processes such as cell differentiation, proliferation, metastasis, and signal transduction in cancer cells." (PMID 38233377, 2024). "Moreover, our findings indicate a significant association between these genes and certain TFs, such as MYC and FOS, which are known to be involved in the processes of proliferation, metastasis and apoptosis in many cancer types." (PMID 37861558, 2023). "Therefore, the JUN and FOS gene families contribute significantly to cancer transformation and cell growth." (PMID 36967404, 2023). "JUN and FOS are part of the transcription factor AP-1, which plays an important role in cell growth and the differentiation and overexpression of these two proteins leads to an increased expression of other oncogenes in several cancer entities." (PMID 37627150, 2023). "Furthermore, high extracellular Ca2+ also stimulated the expression of early response genes such as FOS/FOSB and a unique set of genes associated with malignant tumors, including MAGEC2." (PMID 35355564, 2022). "Moreover, FOS inhibitors were recently observed to induce robust apoptosis in cancer cells harboring a mutant TERT promoter by suppressing GABPB1 and TERT expression." (PMID 35326537, 2022). "The results in CpG-poor hypo-methylated DMRs predicted TF members of the AP-1 family (motif cluster JUN/FOS) in most cancers, those TFs regulate several important cellular functions such as proliferation, differentiation and apoptosis, and their role in tumorigenesis is well established." (PMID 35331302, 2022). "Based on the microarray data, we speculated that the expression of early response FOS and/or FOSB may lead to the expression of cancer progression associated genes such as MAGEC2." (PMID 35355564, 2022). "The miR-1262 rs12740674 C>T genetic variant locating in a potential gene enhancer region, may lead to differential binding of multiple tansfactors, i.e. FOS, and dysregulatory expression of miR-1262 in cancer cells." (PMID 33442421, 2021). "We identified three hub genes (HDAC2, SMARCA4, and FOS) by PPI analysis that previous studies have suggested may be crucial in cancer development." (PMID 32391054, 2020). "Interestingly, although c-FOS is a proto-oncogene, counterintuitively its expression was reduced in the cancer specimens." (PMID 33256002, 2020). "In contrast to the JUN family, FOS proteins appear to play more diverse roles in cancer." (PMID 30658436, 2019). "Collectively, OCT4A regulates FOS and other hundreds of genes (rather different from target genes in PSCs) involved in multiple signaling pathways (such as integrin signaling pathway) in somatic cancer cells." (PMID 29789579, 2018). "Here we provide compelling evidence using both cancer cells with non-edited POU5F1 gene and cancer cells whose POU5F1 gene locus was inserted with a Tag sequence, endogenous OCT4A proteins preferentially bound to the −1826~−1819 bp region of the FOS promoter/enhancer in somatic cancer cells." (PMID 29789579, 2018).
cancer (continued). "Fifteen members of cancer pathways, including FOS, TGFα, FZD8, MMP1, laminin subunit gamma 2, PTGS2, laminin subunit beta 3, ITGA2, laminin subunit alpha 3, VEGFC, WNT2B, heat shock protein 90 beta family member 1, WNT5B, FGF5 and WNT3A, were up-regulated in the MC group." (PMID 30482199, 2018). "Hence, molecular signaling pathways that operate via c-FOS can induce expression of VEGF-D—an example is the capacity of interleukin 7 to promote VEGF-D production in a range of cancer cells via a c-FOS-dependent pathway." (PMID 29300337, 2018). "Because c-FOS plays a key role in cancer progression of various cancer types, including CC, we examined whether its expression is regulated by MSI-2 in CC cells." (PMID 29073938, 2017). "Pathway analysis of the 50 gene NIT signature revealed enrichment for MAPK signalling (DUSP1, JUN, NR4A1 and FOS), cancer specific (COX-2, PGE2, JUN and FOS), apoptosis induction (FOS and JUN) and genomic reformatting following (brain) ischaemia (EGR1 and JUN) pathways." (PMID 27384960, 2016). "Besides, the mRNA expression of MAGEB16, SERPINE1, HSPA2, FOS, involved in the cancer-related signaling pathways, was 1.64, 2.83, 3.62, 2.54 fold changed respectively." (PMID 26879937, 2016). "FOS is highly expressed in different cancers and is a prognostic marker for cancer progression." (PMID 26024509, 2015). "The overexpression of FOS and TNF fixed the fate of the system as they can activate important genes implicated in the regulation of process of adhesion, apoptosis, immune response, cell proliferation and other signaling pathways related with cancer." (PMID 26088082, 2015). "We found that CBX7 negatively or positively regulates the expression of several genes (such as SPP1, SPINK1, STEAP1, and FOS, FOSB, EGR1, respectively) associated to cancer progression, by interacting with their promoter regions and modulating their transcriptional activity." (PMID 24865347, 2014). "The significance of the immediate early gene and oncogenic transcription factor, FOS, as a FoxO target in skeletal muscle during cancer cachexia is currently unknown." (PMID 25539728, 2014). "Therefore, c-FOS inhibition may be an effective treatment strategy for improving the outcomes of patients with MM by eliminating drug-resistant cancer stem cell-like MM cells in MRD." (PMID 40214428, 2025). "Thus, PF/PM may be accurately distinguished from other cancers that are identical to it using c-FOS immunohistochemistry." (PMID 39070491, 2024). "Therefore, consistent with the discussion we propose that MAPKs (MAPK13 and MAPK14) and genes for AP-1 (FOSL1 and FOS) identified from sensitivity analysis of psoriasis are significant genes that might lead psoriasis towards cancer." (PMID 34267747, 2021). "In this study, we identified a set of associated DEGs (CD44, CTGF, DPP4, CRYAB, EGLN3, FGF1, and FOS) with at least one functional enrichment, such as “angiogenesis”, “binding of endothelial cells”, “development of blood vessel”, MAPK signaling, HCM, and pathways in cancer." (PMID 28623314, 2017). "In this comparison, the CREB1, FOS, HSPA5, and JUN genes exhibited a significant downregulation in malignant tumors compared to group 1 (p < 0.05) (Analysis 1)." (PMID 40722651, 2025). "The results suggested that FOS contributed to the progression of LUAD and was generally correlated with adverse outcomes in cancer patients." (PMID 40936936, 2025). "Our studies show that FOS is a main regulator of C0 MAFF+ TCs in LUAD, polarizing macrophages via MIF and rewiring lipid metabolism to support cancer." (PMID 40936936, 2025). "Previous studies have determined a direct role for the SS18-SSX fusion protein in regulating expression of several cancer-related genes, such as EGR1, FOS, IGF2, FZD10, SOX2, UNCX and CDH4." (PMID 39045458, 2024). "FOS showed positive correlations with critical genes such as VEGFA and TGFB1, indicating its possible role in immune regulation and cancer progression." (PMID 39063239, 2024).
cancer (continued). "THz demethylation downregulates FOS, JUN, and CXCL8 genes, which are involved in cancer and apoptosis pathways." (PMID 36967404, 2023). "In contrast, CX3CR1low TEFF highly expressed activator protein-1 (AP-1) family genes (FOS, FOSB, JUNB, JUN and JUND), which were cancer-related transcription factors." (PMID 37080999, 2023). "Across almost all cancer types, the motifs from the cluster JUN/FOS were highly enriched except for BRCA and PRAD." (PMID 35331302, 2022). "In post-treatment tumors, genes such as FOS, JUNB, COL1A2, and DUSP1 have shown to favor cancer proliferation and invasion and were predominantly expressed compared with pre-treatment tumors." (PMID 36505794, 2022). "FOS and ATF proteins are established regulators of proliferation, differentiation and apoptosis in many cancers." (PMID 35511484, 2022). "In other studies, FOS and FOSB were found to increase cancer cell invasion, and JUN was involved in cancer cell invasion and metastasis." (PMID 35037412, 2022). "Curcumin suppresses the other proliferation signaling pathways, such as PI3K, AKT, mTOR, AP1 (JUN and FOS), JNK, JAK/STAT, PKC, CMYC, MAPK, ELK, CDKs, iNOS, and Wnt/β-catenin, which confirmed its vital role in the prevention of cancer progression." (PMID 34485117, 2021). "Further, FOS also promotes increased expression of EGFR (HER1/ErbB1) and affects cell differentiation and proliferation during cancer progression." (PMID 34938177, 2021). "Our research found that the active compounds such as quercetin, kaempferol, beta-sitosterol, and stigmasterol (R)-canadine in Scutellaria baicalensis Georgi play an antigastric cancer role by binding ESR1, FOS, and other genes." (PMID 34421596, 2021). "In ESCC cell lines, we examined all AP-1 transcription factors including JUN, FOS, MAF, and ATF family members and found that FOSL1, MAFK, BATF, and ATF5 are upregulated compared to non-cancer cells." (PMID 34722266, 2021). "The hub gene TYMS is also involved in one carbon pool by folate pathway; FOS, JUN, and CDH1 genes are involved in pathways in cancer; and JUN and FOS genes are involved in the oestrogen signalling pathway." (PMID 32093341, 2020). "In particular, diet-modulated miRNAs were able to target and interfere with several genes mainly involved in cancer signal transduction pathways (e.g., EGFR, RAC1, PLCG1, FOS, NRAS, SOS2, etc.)." (PMID 32911851, 2020). "On the other hand, oncogene and cancer related genes, such as MYC, FOS, JUN, and growth promoting genes were upregulated in U1 AMO, but downregulated in U1 OE." (PMID 31911652, 2020). "We found significant joint over expression of the JUN and FOS proto oncogenes in a cluster of cells for sample ETV6.RUNX1.2, suggesting deregulation in stress/cancer genes." (PMID 32415257, 2020). "ERG also modulates the expression of FOS and PCNA, which are focus molecules in Network IV that includes DNA replication, recombination, and repair, cancer, Organismal injury and abnormalities." (PMID 31303963, 2019). "We found 237 differentially expressed genes (DEGs) including EGR1, FOS, and FOSB, which were three cancer-related transcription factors." (PMID 30228980, 2018). "The HIV TAR RNA in HIV-infected T-cell exosomes is responsible for the pro-tumor effect and expression of the proto-oncogene FOS and TLR3-inducible interferon-stimulated genes (ISGs) in cancer cells, depending on the loop/bulge region of the molecule." (PMID 30389917, 2018). "Based on the results, we found that STAT6, a cancer-related TF, regulated FOS and FOSB, while FOS and EGR1 were coregulated by 2 cancer-related TFs, including BRCA1 and SP1, respectively." (PMID 30228980, 2018). "We show that the mutant TAR RNA with 5-nucleotide substitutions in the bulge and loop sequences, which retains the same stem structure as wild-type TAR RNA35, cannot induce expression of FOS and DEFB103 in cancer cells." (PMID 30389917, 2018).
cancer (continued). "We intersected 237 common DEGs and curated 36 cancer-related TF families to get three differentially expressed TFs (EGR1, FOS, and FOSB) in HCC." (PMID 30228980, 2018). "Enrichment of similar factors was found for cancer and aging, for example, EP300, FOS, and JUN, among others." (PMID 29504244, 2018). "Using multiple cohorts profile datasets and integrated bioinformatical analysis, we identified commonly 237 DEGs, and finally found EGR1, FOS, and FOSB, 3 cancer-related TFs, which were downregulated in HCC." (PMID 30228980, 2018). "While EINCR1 is upregulated in the cancer samples, both FOS and FOSB show reduced expression in cancer samples." (PMID 28732076, 2017). "The second network, involved in cancer, has MYC as the central node (score = 144.3), followed by CDKN1A (score = 119.5) and FOS (score = 118.4)." (PMID 29216278, 2017). "Subsequently, p-STAT3 can induce the downstream target genes, such as CCL2, CCL5, ICAM-1, SNAI1, chitinase-3-like 1 (CHI3L1), FBJ murine osteosarcoma viral oncogene homolog (FOS), and Skp2, that promote various cellular processes for cancer progression." (PMID 28157698, 2017). "FOS is a downstream gene in the MAPK pathway, which has a direct relationship with cancer cell proliferation and differentiation." (PMID 28114404, 2017). "We also found a number of genes whose expression follows this pattern: high-grade cancers < low-grade cancers < normal tissue, such as ALDH1L1, WIF1, ACSL1, FOS, and ABLIM1 in at least four cancer types." (PMID 28427185, 2017). "The expression of a gene that is involved in cancer and MAPK signaling pathways, FOS (FBJ murine osteosarcoma viral oncogene homolog), is increased by miR-101 under hypoxic conditions." (PMID 26571238, 2015). "The perturbation in the network through overexpression of important regulatory proteins, such as FOS and TNF, determine the dynamic of the network and activate genes involved in different signaling pathways that play important roles in cancer." (PMID 26088082, 2015). "Given the overriding importance attributed to FOS and TNF in cancer biology and their high topological measures in the PPI network, we chose these genes to performed perturbation simulations of knockout and overexpression in the system." (PMID 26088082, 2015). "Our results provide the first evidence that, in aggressive EC cells, miR-101 governs multiple malignant phenotypes including proliferation, migration, invasion and cancer stemness, at least partly via downregulating the expression of EZH2, MCL-1 and FOS." (PMID 25153722, 2014). "In fact, FOS, FOSB and EGR1 are proteins that have been reported to be down-regulated in several human carcinomas suggesting a critical role of these proteins in cancer progression." (PMID 24865347, 2014). "Contrary to other cancers, the well-known anti-apoptotic BCL2, the FOS oncogene and the multidrug resistance gene ABCB1 (ATP-binding cassette sub-family B member 1) were down-regulated." (PMID 19662092, 2009). "In contrast, FOS, EGR1, and JUN inhibit apoptosis, exacerbating cancer progression." (PMID 40740774, 2025). "However, these cells showed decreased expression of inflammatory markers CD69, FOS and DUSP1 in cancer patients, thus indicating a less active inflammatory profile." (PMID 40340807, 2025). "Targeting the recruitment of these complexes on gene promoters may be a promising therapy in several cancer types, since upon activation, ELK1 promotes the expression of several oncogenes including EGR1 and FOS." (PMID 40862737, 2025). "In order to determine transcription factors in cancer-associated fibroblast activation, which play a role in cell proliferation and cancer progression, we evaluated the expression of several transcription factors, including SOX9, POU5F1, ZEB1, JUN, and FOS in the HRTPT cell line exposed to arsenite." (PMID 40699854, 2025).